ITM2B (integral membrane protein 2B)
Diseases named in the same sentence as ITM2B in open-access papers (continued):
Sharing a sentence is not in itself a finding about the gene and the disease.
deafness (2 papers, 2006 to 2022). An inherited or acquired condition characterized by the complete loss of the ability to hear from one or both ears. "For example, the "perception of sound" (GO:0007605) associated with ITM2B comes from a spkw2go mapping as this gene was implicated in causing deafness." (PMID 16674810, 2006). "The deafness gene panel also detected other gene variants (i.e COL1A1, ITM2B), but their pathogenicity was uncertain as per the American College of Medical Genetics guidelines." (PMID 36064591, 2022).
familial Alzheimer disease (2 papers, 2012 to 2016). A degenerative disease of the brain that causes gradual loss of memory, judgment, and the ability to function socially. "Mutations in BRI2/ITM2b genes cause Familial British and Danish Dementias (FBD and FDD), which are pathogenically similar to Familial Alzheimer Disease (FAD)." (PMID 26942869, 2016).
retinal disease (2 papers, 2017 to 2019). "Further studies of GLUT9 and ITM2B interactions in the retina might eventually help uncover the pathogenic mechanism(s) of retinal disease associated with ITM2B mutations and help clarify the role of ocular uric acid homeostasis in retinal disease." (PMID 31695625, 2019).
Retinal dystrophy (2 papers, 2019 to 2021). Retinal dystrophy is an abnormality of the retina associated with a hereditary process. "APLP2 is particularly interesting since its deletion in the mouse retina induces a phenotype similar to the retinal dystrophy observed in subjects carrying the ITM2B c.782A>C, p.Glu261Ala mutation notably with similar electroretinogram alterations." (PMID 34446781, 2021). "Further investigations using retinal organoids derived from these iPSCs will help to better characterize the ITM2B interactome during retinal development and the impact of the ITM2B-retinal dystrophy mutation on protein interactors." (PMID 34446781, 2021). "More recently, another autosomal dominant mutation in ITM2B (c.782A>C, p.Glu261Ala) has been reported in an unusual retinal dystrophy associated with retinal ganglion cell abnormalities, inner retinal and cone dysfunctions." (PMID 34446781, 2021). "The ITM2B-retinal dystrophy mutation could lead to a loss of interaction between APLP2 and the mutant ITM2B inducing a similar phenotype as the Aplp2−/− mice." (PMID 34446781, 2021). "Indeed, among other retinal abnormalities, affected subjects carrying the retinal dystrophy-related ITM2B missense mutation exhibit an early onset ganglion cell loss." (PMID 34446781, 2021). "The ITM2B point-mutant associated with retinal dystrophy (RD) exhibited attenuated inhibitory effects predominantly on GLUT9b-mediated urate transport, suggesting that this form of genetic retinal dystrophy might be associated with altered urate transport." (PMID 31695625, 2019). "Recently, our group generated induced pluripotent stem cell lines (iPSCs) from a subject affected with the ITM2B-related retinal dystrophy and his unaffected sibling." (PMID 34446781, 2021). "Mutations in the gene encoding ITM2B have been associated with FBD, FDD, and an autosomal dominant form of retinal dystrophy." (PMID 31695625, 2019). "ITM2B is a ubiquitously expressed, N-glycosylated transmembrane regulatory protein, involved in familial dementias and retinal dystrophy; the function of TMEM85 is less defined." (PMID 31695625, 2019).
Anxiety (1 paper, 2015). Intense feelings of nervousness, tension, or panic often arise in response to interpersonal stresses. "As was the cases with the RNA-seq data, twins with higher anxiety scores in the replication set showed higher expression levels of ITM2B." (PMID 26274327, 2015). "The MZ twin discordance analysis showed statistically higher significant expression of exons 5 and 6 in the ITM2B (BRI2) gene for the anxiety cohort." (PMID 26274327, 2015).
autoimmune hypophysitis (1 paper, 2022). "Moreover, recent studies have identified some autoantibodies expressed in human pituitary gland and associated with autoimmune hypophysitis: anti-guanine nucleotide-binding protein G subunit alpha (GNAL), anti-integral membrane protein 2B (ITM2B), and anti-ZCCHC8." (PMID 36612243, 2022).
cerebral small vessel disease (1 paper, 2021). Cerebral small vessel disease is the term currently used to pathological processes that affect the brain parenchymal circulation (arterioles, capillaries, and veins). "For patients carrying variants outside EGFr region, no potential pathogenic mutation were identified in several other genes known to be common causal of cerebral small-vessel disease or vascular dementia (HTRA1, TREX1, COL4A1, COL4A2, GLA, APP, and ITM2B) by targeted next-generation sequencing." (PMID 34335700, 2021).
COVID-19 (1 paper, 2022). A disease caused by infection with severe acute respiratory syndrome coronavirus 2. "For integral membrane protein 2B, a recent serological study demonstrated that the antibodies produced by COVID-19 patients showed an unexpected immune response against integral membrane proteins, which can be used to detect SARS-CoV-2 variants or test vaccine effectiveness." (PMID 36091008, 2022).
diabetes (1 paper, 2024). "In diabetic mouse models, ITM2B expression is also upregulated, suggesting its role in diabetes and neuropathy." (PMID 39639394, 2024).
hereditary amyloidosis (1 paper, 2021). Hereditary amyloidosis refers to a group of inherited conditions that make up one of the subtypes of amyloidosis. "Mutations of GSN and ITM2B have been identified as the causes of hereditary amyloidosis." (PMID 34551193, 2021).
hyperuricemia (1 paper, 2026). An abnormally high level of uric acid. "Our findings that hyperuricemia is linked with ITM2B truncation‐regulated migrasome formation and that both migrasomes and ITM2B truncation maintain higher levels in the urine of RCC patients are anticipated to provide crucial insights." (PMID 41319268, 2026). "In a mouse model, physiological hyperuricemia enhanced ITM2B cleavage to facilitate migrasome formation and activate caspase‐7 migracytosis, thereby exacerbating RCC growth." (PMID 41319268, 2026). "This study not only highlights novel functions of ITM2B truncation in migrasome formation and active caspase‐7 migracytosis but also elucidates the role of hyperuricemia in RCC progression via regulation of the ITM2B truncation–migrasome axis." (PMID 41319268, 2026). "Together, these in vivo results demonstrate that physiological hyperuricemia‐induced ITM2B cleavage promotes tumor growth through migrasome formation and migracytosis of c‐CASP7." (PMID 41319268, 2026). "Pathologically, hyperuricemia promotes ITM2B‐dependent migrasome formation to accelerate RCC progression." (PMID 41319268, 2026). "Consequently, hyperuricemia increased IL‐6 pathway activity in ITM2B‐expressing allografts, whereas this effect was diminished in ITM2BI115A‐expressing allografts." (PMID 41319268, 2026). "Overall, this study highlights a novel role of ITM2B truncation in remodeling the TME through the induction of migrasome formation and active caspase‐7 migracytosis and explains hyperuricemia‐induced poor survival in RCC patients via the ITM2B truncation–migrasome axis." (PMID 41319268, 2026). "We finally determined whether physiological hyperuricemia aggravated the growth of RCC tumors through ITM2B truncation in vivo." (PMID 41319268, 2026). "Physiologically, hyperuricemia enhances ITM2B cleavage to aggravate RCC growth." (PMID 41319268, 2026).
liposarcoma (1 paper, 2024). A usually painless malignant tumor that arises from adipose tissue. "The use of sWGS can reveal that myxoid pleomorphic liposarcomas exhibit complex chromosomal alterations, particularly the loss of 13q14, which encompasses the RB1, RCTB2, DLEU1, and ITM2B genes." (PMID 39473659, 2024).
renal carcinoma (1 paper, 2026). A carcinoma arising from the epithelium of the renal parenchyma or the renal pelvis. "In cancer cell line encyclopedia (CCLE) database, the renal cancer cell lines exhibited the highest ITM2B protein level among various cancer cell lines." (PMID 41319268, 2026).
renal cell carcinoma (1 paper, 2026). "In the Renca cell‐derived orthotopic renal cell carcinoma mouse model, ITM2B knockdown retarded tumor growth through the inhibition of tumor cell proliferation, as indicated by Ki67 immunostaining." (PMID 41319268, 2026). "This study identifies truncated ITM2B as a regulator of migrasome formation in renal cell carcinoma (RCC) cells." (PMID 41319268, 2026). "Furthermore, we collected 18 pairs of clinical RCC samples, including renal cell carcinoma samples and corresponding para‐carcinoma samples, to analyze ITM2B expression patterns." (PMID 41319268, 2026). "Here, it is demonstrated that in renal cell carcinoma (RCC) cells, N‐terminal truncation of ITM2B facilitates migrasome swelling through the recruitment of TSPAN4 and promotes migrasome formation." (PMID 41319268, 2026).
sleep disorder (1 paper, 2025). A change from the patient's baseline sleeping pattern, in the hours slept and/or an alteration/dysfunction in the stages of sleep. "Next, the homology analysis revealed that the mmu_circ_0005429 and the hsa_circ_0006620 (linear transcript ITM2B) have identity reached 89.2%, and the increased expression of hsa_circ_0006620 in the serum of TBI patients was related to sleep disorders." (PMID 39962534, 2025).
neurodegenerative disease (11 papers, 2015 to 2026). A disorder of the central nervous system characterized by gradual and progressive loss of neural tissue and neurologic function. "Other significantly downregulated genes were Resp18, Rtn1, Psap, Ubb, Aplp1, Cst3 and Itm2b, which are all associated with neurodegenerative diseases." (PMID 38017352, 2024). "Several genes involved in amyloid production were also found to be dysregulated by RH, including Aplp, Rtn1 and Itm2b, all of which have been associated with amyloid beta (Aβ) protein formation, and Resp18, Psap, Ubb and Cst3, all of which are associated with neurodegenerative diseases." (PMID 38017352, 2024). "In neurodegenerative diseases, ITM2B and its truncations play distinct roles in processing amyloid‐beta precursor (APP)." (PMID 41319268, 2026). "ITM2B (Integral Membrane Protein 2B) is a widely expressed transmembrane protein, playing significant roles in the nervous system, particularly in neurodegenerative diseases." (PMID 39639394, 2024). "Together, these data support a role for ITM2B/BRI2 in the microglial response to damage and neurodegenerative diseases such as AD." (PMID 39546024, 2024). "The BCL6 transcriptional repressor targets the ITM2B gene, which has important links to neurodegenerative diseases such as AD." (PMID 36414996, 2022).
tumor (10 papers, 2017 to 2026). "To further explain the unique function of truncated ITM2B in tumor growth, we first employed immunofluorescence analysis to elucidate the subcellular localization of ITM2B and its mutations." (PMID 41319268, 2026). "Through analysis of ITM2B mRNA expression using the cancer genome atlas (TCGA) databases, we found significantly higher ITM2B mRNA levels in kidney tissues and their corresponding tumor tissues." (PMID 41319268, 2026). "Ki67 expression also showed the expected results in different groups, suggesting that ITM2B truncation accelerated tumor growth through migrasomes." (PMID 41319268, 2026). "Physiological hyperuricemia induced ITM2B cleavage, which further accelerated tumor growth in a mouse model." (PMID 41319268, 2026). "We detected PDPK1‐AS, SOS1‐IT1, SMARCA4‐AS, FLOT2‐AS, CSRP1‐AS1, and ITM2B to be upregulated in tumor tissue compared with adjacent mucosa." (PMID 40635521, 2025). "Finally, the effects of ITM2B truncation‐induced active caspase‐7 migracytosis on tumor growth were also determined." (PMID 41319268, 2026). "Considering the critical roles of migrasomes in intercellular communication, ITM2B truncation‐dependent migrasomes from RCC cells may be internalized by other cell types within the tumor microenvironment (TME)." (PMID 41319268, 2026). "Relative to Post-OP levels, 64 uEV proteins changed significantly at GBM tumour recurrence (p ≤ 0.05), including three proteins (GGH, GRN, ITM2B) that increased by ≥2-fold in the REC group (adjust p-val≤0.05)." (PMID 38212481, 2024). "Tumor tissues obtained from the corresponding allografts clearly revealed that hyperuricemia facilitated ITM2B cleavage in ITM2B‐expressing allografts but not in ITM2BI115A‐expressing allografts." (PMID 41319268, 2026). "While the exact mechanisms are still unclear, ITM2B was identified as a downstream effector of miR-143 in GBM cells, which has a demonstrated role in GBM invasion; the specific inhibition of miR-143 reduced GBM tumour growth and progression in vivo." (PMID 38212481, 2024). "Furthermore, ITM2B1‐115 overexpression in ITM2B‐knockdown Renca cells significantly promoted tumor growth, whereas ITM2BI115A did not, as reflected by corresponding Ki67 expression levels." (PMID 41319268, 2026).
cancer (9 papers, 2012 to 2026). A tumor composed of atypical neoplastic, often pleomorphic cells that invade other tissues. "The physiological functions of ITM2B are primarily studied in the context of neurological disorders, but their roles in cancers are largely overlooked." (PMID 41319268, 2026). "The functions of ITM2B have long been focused on regulating neurological dysfunction, but are overlooked in the context of cancer development." (PMID 41319268, 2026). "Immunohistochemical analysis of ITM2B expression in carcinoma tissues and corresponding para‐carcinoma tissues of RCC patients indicated that the ITM2B protein level in carcinoma tissues decreased compared to that in para‐carcinoma tissues." (PMID 41319268, 2026). "The results revealed lower levels of full‐length ITM2B in the carcinoma samples than those in the para‐carcinoma samples, whereas the levels of truncated‐ITM2B remained high in the carcinoma samples." (PMID 41319268, 2026). "Clinically, RCC tissues tend to produce ITM2B truncations compared with corresponding para‐carcinoma tissues." (PMID 41319268, 2026). "Compared with para‐carcinoma samples, clinical RCC samples presented lower full‐length ITM2B levels but maintained high ITM2B truncation levels, further supporting the protumoral role of ITM2B truncation." (PMID 41319268, 2026). "Based on the literatures included in PubMed, GPR12, ITM2B, ZNF24, and NSL1 were selected as the candidate targets due to the low expressions in various cancers." (PMID 37789353, 2023). "In various cancer cell lines, ITM2B was found to possess a broad‐spectrum cleavage property, and RCC cells such as 786‐O, A498, and ACHN exhibited relatively high ITM2B expression levels, particularly in the truncated‐ITM2B case." (PMID 41319268, 2026). "The quantitative analysis of the western blot further supported a decreasing trend for full‐length ITM2B but not for truncated‐ITM2B in the carcinoma samples (left & middle)." (PMID 41319268, 2026).
infection (4 papers, 2008 to 2021). The state of being infected such as from the introduction of a foreign agent such as serum, vaccine, antigenic substance or organism. "For rDEN2Δ30 infection, higher baseline expression of myeloid nuclear differentiation antigen (MNDA), and cell surface associated cellular processes such as tetraspanin CD37, integral membrane 2B (ITM2B), and genes involved in autophagy (VMP1) was associated with protection from rash." (PMID 34031380, 2021).
neurological disorders (3 papers, 2017 to 2026). "Several of these such as NOTCH2, APP, ITM2B and PTGDS have been implicated in neurological disorders." (PMID 36185601, 2022).
retinal disorder (1 paper, 2021). Any disease or disorder of the retina. "ITM2B is an intriguing protein involved in different cerebral and retinal disorders." (PMID 34446781, 2021).
ITM2B also shares sentences with these, for which no sentence is quoted: Cognitive impairment (5 papers); familial British dementia (5); Tauopathies (4); cognitive decline (3); pneumonitis (3); Autoimmunity (2); Parkinson disease (2); type 2 diabetes (2); acute myeloid leukemia (1); amnesia (1); amyotrophic lateral sclerosis (1); avian influenza (1); breast carcinoma (1); cervix carcinoma (1); Chanarin-Dorfman syndrome (1); colon cancer (1); frontotemporal dementia (1); interstitial lung disease (1); melanoma (1); meningioma (1); neuroblastoma (1); neuropathy (1); osteosarcoma (1); rectal cancer (1); respiratory disease (1); scrapie (1); Senile plaques (1); systemic amyloidosis (1); tuberculosis disease (1); vascular dementia (1).